IL6 (interleukin 6)
Diseases named in the same sentence as IL6 in open-access papers (continued):
Sharing a sentence is not in itself a finding about the gene and the disease.
ZIKV infection (64 papers, 2017 to 2025). "ZIKV infection was associated with concomitant secretion of inflammatory mediators linked with central nervous system inflammation such as IL-6, TNF-α, IL-1β, iNOS and NO." (PMID 30359409, 2018). "This possibility is supported by the fact that we do see an increase in IP-10 and IL-6 in the placental villi and an increase in IL-6 in the chorionic plate but no increase in any pro-inflammatory cytokines in the decidua associated with ZIKV infection." (PMID 38515747, 2024). "Hence, we examined the ISGs transcript levels for DDX58, IFIT1, ISG15, and IFNB1, and analyzed the transcript levels of inflammatory cytokines including TNF-α and IL-6 that are associated with severe symptoms during ZIKV infection." (PMID 34745057, 2021). "In the same study, ZIKV infection was associated with concomitant secretion of inflammatory mediators linked to CNS inflammation and alterations in endothelial and microvascular permeability, such as IL-6, TNF-α, IL-1β, iNOS, and NO." (PMID 31620112, 2019). "ZIKV infection induced the expression of proinflammatory cytokines, including interleukin-1β (IL-1β), IL-6, gamma interferon, and tumor necrosis factor alpha, in the brains of Ifnar1−/− mice." (PMID 37191498, 2023). "In summary, ZIKV infection of the brain induced the expression of proinflammatory cytokines, including IL-1β, IL-6, IFN-γ, and TNF-α, in Ifnar1−/− mice." (PMID 37191498, 2023). "We treated the cells at 24 h post ZIKV infection with IL6 or IL8 at a final concentration of 0, 25, 50, and 100 ng/mL." (PMID 38051045, 2023). "Expression analysis via qRT-PCR showed that ZIKV infection induced significant upregulation of each of the cytokines analyzed, including Ifna6, Ifnb, Ifng, Il1b, Il6, and Tnfa." (PMID 35462541, 2022). "In line with a previous observation, there was an increased production of IL-6 in monocyte-derived macrophages during ADE of ZIKV infection compared to mock infection (13.6 vs. 3.1 pg/mL, p = 0.003)." (PMID 36560779, 2022). "ZIKV infection also induces IL-6 secretion, most probably through the activation of the IL-6/STAT3 signaling pathway, which plays a key role in regulating inflammatory host immune responses during infections." (PMID 36483552, 2022). "ZIKV infection increases the levels of a series of cytokines (IL-1α, IL-6, IL-9, IL-10, IL-12p70, and IFN-γ) and chemokines (CCL2, CCL3, CCL4, CCL5, CCL11, and CXCL1) in mouse brain." (PMID 34399779, 2021). "To address this assumption, we stimulated control A549 cells with different concentrations of IL-6 prior to ZIKV infection, with the lowest concentration corresponding to IL-6 amounts released upon ZIKV infection." (PMID 33658344, 2021). "Similar to data obtained from RNA-sequencing, qRT-PCR validated that ZIKV infection induces up-regulation of interferon gamma induced protein 10 (IP-10), interleukin-6 (IL-6), 2'-5'-oligoadenylate synthetase 1 (OAS1) and interferon-β (IFN-β) genes." (PMID 32902370, 2020). "Herein, we reported significant increase in the inflammatory molecules, RANTES, MCP-1, IP-10, IL-8 and IL-6 with ZIKV infection in glial cells." (PMID 30735502, 2019). "We observed that ZIKV infection induced a pro-inflammatory profile in SH-SY5Y cells by triggering the secretion of higher levels of the pro-inflammatory cytokine IL-6 and the chemokine MCP-1, since initial times of infection (24 h)." (PMID 31882804, 2019). "ZIKV infection in primary Tupaia cells induced an upregulation of cytokine mRNA levels over the infection time, including those of IL-6, IL-8, TNF-α, IFN-β, CXCL9, and MX1, where IL-6, IL-8, and TNF-α mRNA levels were significantly elevated 6 h post-infection." (PMID 31842286, 2019). "ZIKV infection induced increased SC expression of IL-6, interferon (IFN)β1, IFN-λ, IFIT-1, TNFα and IL-23A mRNAs as well as IFN-λ receptors and negative regulators of IFN signaling." (PMID 31289325, 2019).
ZIKV infection (continued). "Cytokine profiles in acute ZIKV infections were estimated using a multiplex bead analysis assay which measured interleukin (IL) 1β, IL-2, IL-4, IL-6, IL-8, IL-9, IL-10, IL-13, and IL-17." (PMID 30682026, 2019). "ZIKV infection of HBMECs and RECs led to activation of several proinflammatory cytokines including IL-6, CCL1, and CCL5." (PMID 31249527, 2019). "Top selected ZIKV infection-associated genes from RPE cells are shown in a heatmap that includes multiple immune response genes, such as CCL5, CXCL11, CXCL1, IFNB1, IL6 and TNFSF10." (PMID 30046058, 2018). "In addition to these cytokines, GM-CSF, IL-1B, IL-2, IL-6, IL-17, and IL-22 have been observed in the acute phase of Zika virus infection." (PMID 41417343, 2025). "Here, we observe ZIKV infection to elevate secretion of the principal triad of pro-inflammatory cytokines (IL-1, IL-6, and TNF-alpha) by both brain tumour cell lines, in addition to many other cytokines that we report for the first time to be a component of oZIKV infection." (PMID 40240536, 2025). "While IFN-β and IL-6 did significantly alter the expression of some target genes, significant DEGs following these treatments did not closely follow the pattern of downregulation or upregulation induced by ZIKV infection." (PMID 35462541, 2022). "The samples from pregnant women with ZIKV infection included in this study showed increases in all anti-inflammatory cytokines (IL-10), and some pro-inflammatory cytokines (IL-6, IFN-γ, IFN-α, and IL-17A), chemokines (CXCL10, CCL2, CXCL9, and CXCL8), and receptors (IL-1RA and IL-2R)." (PMID 33430059, 2021). "First, we examined the expression pattern of IL-6 and IL-8 during ZIKV infection." (PMID 33207682, 2020). "We found that ZIKV infection of HUVECs leads to increased levels of IL-6 and IL-8 production." (PMID 31068911, 2019). "The results obtained in the present study indicate that ZIKV infection induces neuroinflammation in microglia which leads to the production of IL-6, TNF-α, IL-1β and IFNs, molecules with strong pro-inflammatory effects that feature among the most potent neuroinflammatory cytokines." (PMID 30359409, 2018). "In addition to bone formation biomarkers, elevated levels of IL6 comparable to that described for other arthritogenic arboviruses were also observed following ZIKV infection." (PMID 30451958, 2018). "In addition, ZIKV infection significantly induced seminal inflammatory cytokines including IL-6, IL-10, G-CSF and GM-CSF (ZIKV vs. Mock)." (PMID 29447264, 2018). "In addition, ZIKV infection induces high levels of IL-17, IL-6 and IL-1β." (PMID 35215843, 2022). "Indeed, ZIKV infection under conditions of antibody-mediated sequestration of IL-6, which was released from the cells into the culture supernatant, resulted in ∼3-fold-enhanced STAT1 phosphorylation (top blot), whereas STAT3 phosphorylation and SOCS3 expression were significantly reduced." (PMID 33658344, 2021). "In this study, IL-6 production may contribute to the host defense against ZIKV infection." (PMID 33667230, 2021). "Again, also, high levels of IFN-γ, TNF-α, IL-6, TGF-β and IL-10 have been observed during acute ZIKV infection in pregnant women." (PMID 37512810, 2023). "Inflammatory cytokines (e.g., IL-1β, IL-6, and TNF-α) induced following Zika virus infections in human macrophages also upregulate CH25H in type I IFNs in an independent manner." (PMID 37631994, 2023). "In U87MG cells, TMEM120A overexpression increased the transcription of IL6, IL8, and IFIT2 to a similar level as STING overexpression induced after ZIKV infection." (PMID 35013224, 2022). "Proinflammatory cytokines such as interleukin-6 (IL6) can function as neurotoxic factors and are produced by activated CNS glial cells in response to ZIKV infection." (PMID 35379362, 2022).
ZIKV infection (continued). "ZIKV infection promoted muscle lesions, with infiltration of inflammatory cells, along with an upregulation of proinflammatory cytokines (TNF, IL-1β, and IL-6) and chemokines (RANTES and MCP-1) involved in monocyte/macrophage recruitment (39, –, 41)." (PMID 34468171, 2021). "Even both of them induced apparent liver inflammation, ZIKV infection showed a more severe inflammatory response than DENV-2 infection based on the inflammation scores and the gene expression levels of IL-1β, TNF, IL-6, and TGFβ-2 in liver." (PMID 31191474, 2019). "Cytokine kinetics in our study mimics the kinetics reported in clinical cases of ZIKV where RANTES, IL-6, IP-10 and IFN-β were elevated both in acute and convalescent phases of ZIKV infection, albeit higher levels were detected during the acute phase." (PMID 30735502, 2019). "Moreover, an increase in the TNF and IL-6 families of cytokines may have implications on other important testicular cell functions during ZIKV infection, including steroidogenesis and leukocyte transmigration, and therefore further investigation in this area is also warranted." (PMID 29880853, 2018). "We show that the immune response during the acute phase of ZIKV infection is polyfunctional and broadly inflammatory, as evidenced by significantly elevated levels of IL-4, IL-17, IFN-γ, IL-1β, IL-1Ra, TNF-α, and IL-6 in patients as compared to controls." (PMID 29768624, 2018). "Using a qRT-PCR assay, high expression levels of pro-inflammatory cytokine genes, including IL6, IL15, IFNγ, TNFα, CXCL15, IL18, and IL1β, were confirmed in ZIKV-infected placentas, suggesting that ZIKV infection may trigger placental inflammation." (PMID 41263557, 2025). "As a proof of concept, isolated HB cells from healthy term placenta secreted elevated pro-inflammatory cytokines such as IL-6, MCP-1, IP-10, and IFN-α upon in vitro infection with Zika Virus (ZIKV), even if HB cells are permissive for ZIKV infection and replication." (PMID 37512810, 2023). "We observed A549 lacking RIG-I failed to induce IFN-I, IFN-III, ISGs, and IL6 transcriptions during ZIKV infection, confirming that RIG-I is necessary for activation of antiviral immune response." (PMID 36311766, 2022). "Rather, we found that MOCCI, WT, and ATGmut-mRNA were also sufficient to lower the secretion of IL-6, MCP-1, and even IL-8 upon challenge with bacterial endotoxin LPS, which was more potent in inducing cytokine secretion in HAECs compared to DENV/ZIKV infections." (PMID 33837217, 2021). "It has been reported that Zika fever increases circulating IL-6 levels without changing IL-10 levels." (PMID 33430059, 2021). "Moreover, WNV and ZIKV infection each led to inhibition of pY-STAT1 and 3 in response to human and mouse IL6, and of pY-STAT6 following IL4 treatment." (PMID 32272626, 2020). "HBCA infection with another flavivirus, Zika virus, is associated with only limited activation of immune cytokine/chemokine response, but ZIKV infection induces the highest upregulation of CXCL10, IL-6, 8, 12, and CCL5 (RANTES), which corresponds with the observations in TBEV-infected HBCA." (PMID 31699097, 2019). "In our study, levels of several immune markers, such as IFN-α, IL-12, IL-6, IL-17, IL-10, IL-5, IL-2R, ST2/IL-1R4, CCL2, CCL3, CXCL9, M-CSF and E-Selectin, were significantly higher in presymptomatic/asymptomatic ZIKV infection (A-ZIKV group) when compared to the NI control group." (PMID 31748599, 2019). "Using hNPCs, we were not able to detect production and release of IL-6 upon ZIKV infection." (PMID 33658344, 2021). "ZIKV infection induced in nonpregnant women significantly higher levels of the anti-inflammatory cytokine IL-10, and increased pro-inflammatory cytokines IL-6, IL-2, IFN-α, and IFN-γ, and decreased levels of IL-1β in relation with uninfected, nonpregnant women." (PMID 33430059, 2021).
ZIKV infection (continued). "We do not know whether lower levels of IL-1β, IL-6, IL-8, IL-10, IL-12, IL-13, IL-17A, TNF, and IFN-γ in ZIKV offspring at 32 days were caused by subclinical in utero ZIKV infection or maternal cytokine background." (PMID 31725819, 2019). "ZIKV infection induced a clear antiviral immune response in these cells as shown by the production of high levels of IFN-α, IFN-β and IFN-γ, as well as neurotoxic factors such as TNF-α, IL-1β and IL-6 during the first hours of infection with maximum levels at 48 hpi." (PMID 30359409, 2018). "ZIKV infection triggered the upregulation of multiple cytokines in humans during acute phase of infection that we were able to characterize by Luminex assay, including IP-10, IL-5, GM-CSF, TNF-α, IL-15, IL-10, MIP-1α, IFN-γ, IL-6, IL-1RA, IL-2, MIG, IFN-α, IL-2R, and IL-4." (PMID 30333476, 2018). "In addition, proinflammatory gene transcription induced after RIG-I activation such as IL6 and NFKBIA is independent of DNA-PKcs in A549 cells upon ZIKV infection, but dependent in RPE cells lacking DNA-PKcs." (PMID 36311766, 2022).
aneurysm (63 papers, 2008 to 2026). Bulging or ballooning in an area of an artery secondary to arterial wall weakening. "Previous research has shown that increased serum IL-6 levels are positively associated with aneurysm size in patients with AAA." (PMID 41557627, 2026). "It appears that genetic evidence for benefit of IL6 signaling inhibition on aneurysm risk is specific to AAA." (PMID 39633572, 2025). "Particularly, IL-6 is recognized not only for its diagnostic utility but also as a prognostic marker in aneurysm patients treated with stent grafts." (PMID 39857067, 2025). "Clinical studies have indicated that elevated levels of TNF in the serum of AAA patients are significantly associated with AAA symptoms, and levels of IL-6 and IL-8 are positively correlated with aneurysm diameter." (PMID 38111889, 2023). "For instance, coil coatings with IL-6 or with osteopontin have been shown to positively regulate monocyte chemotactic protein 1, and were associated with good aneurysm healing in a mouse model." (PMID 37533024, 2023). "The present study suggested that aneurysms in different locations respond differently to inflammation caused by IL6 signaling." (PMID 34168680, 2021). "Shimada and coworkers showed that use of the peroxisome proliferator-activated receptor-γ (PPARγ) pioglitazone in a mouse model protects against aneurysm rupture, and that this was associated with a reduction of IL-6 mRNA levels." (PMID 33923626, 2021). "Finally, genetic polymorphisms of the IL-6 gene have been associated with aneurysm formation in British, Chinese and other populations." (PMID 33923626, 2021). "However, in our in vitro studies, IL-6 expression, for example, was decreased in NOR1-deficient macrophages, and inhibition of IL-6 has been demonstrated to prevent angiotensin II-induced aneurysm formation." (PMID 29047330, 2017). "Some conflicting effects of IL-6 deficiency on blood pressure may be influenced by changes in aortic structure and death associated with aneurysm rupture such that a moderate degree of selection bias is introduced if the incidence of aneurysm is not considered or properly measured." (PMID 29186034, 2017). "They proposed that necrotic VSMCs in aneurysms can release IL-1β, inducing IL-6 production, thereby promoting vascular inflammation and accelerating aneurysm progression." (PMID 40244203, 2025). "The expression of proinflammatory cytokines, such as IL-1β and IL-6, was elevated in the aneurysm and circulating system of mice with AAA, which was restrained after ATL-I treatment." (PMID 39958337, 2025). "Two studies reported that significantly smaller aneurysms developed after an IL-6 blocking antibody was administered in the elastase perfusion model and an IL-6R blocking antibody was given in the calcium chloride model." (PMID 36289670, 2022). "A pooled analysis of available data from 1001 AAA cases and 1129 controls showed significantly higher IL-6 levels in aneurysm patients as compared to controls." (PMID 36289670, 2022). "A persistent elevated IL-6 level induces overexpression of multiple proteolytic enzymes (such as metalloproteinase), which can weaken cerebral vessel walls and lead to aneurysm formation." (PMID 36675669, 2022). "Four studies testing the effect of IL-6 or IL-6R inhibition in two different aneurysm models were identified." (PMID 36289670, 2022). "As there is consensus that CAG seems to inhibit macrophage infiltration and expression of pro-inflammatory cytokines, we would have expected to detect lower mRNA expression levels of IL-6 in the CAG-treated aneurysms." (PMID 35203568, 2022). "IL-6 was increased in perianeurysmal blood compared to sheath blood for human samples at time of aneurysm treatment with mean difference 0.269 (t = 3.001, p = 0.024)." (PMID 36114540, 2022). "Our results indicated that Gal-3 was an independent variable for identifying subaneurysmal aortic dilatation and large aneurysms compared with IL-6." (PMID 34136544, 2021).